HDAC6 (histone deacetylase 6)
Diseases named in the same sentence as HDAC6 in open-access papers (continued):
Sharing a sentence is not in itself a finding about the gene and the disease.
Thrombocytopenia (2 papers, 2017 to 2018). A reduction in the number of circulating thrombocytes. "From our data, it is expected that HDAC6 inhibition will lead to a milder thrombocytopenia than with pan-HDACi because HDAC6 inhibition will alter only late stages of megakaryopoiesis." (PMID 29176689, 2017). "In future clinical trials, it will be important to determine if the thrombocytopenia is related to the specific HDAC6 inhibition or to an off-target effect of the inhibitor on other HDAC." (PMID 29176689, 2017). "Additionally, unlike other HDAC inhibitors, the HDAC6 inhibitor does not appear to be associated with any toxicity effects, such as nausea, thrombocytopenia or fatigue, making HDAC6 an excellent therapeutic target." (PMID 30046381, 2018).
vascular dementia (2 papers, 2022 to 2025). A degenerative vascular disorder affecting the brain. "Administration of donepezil has been found to protect against vascular dementia by inhibiting the nuclear translocation of histone deacetylase 6 (HDAC6) and the binding of HDAC6 to BDNF promoter IV, which enhances BDNF expression." (PMID 35090576, 2022).
ZIKV infection (2 papers, 2024 to 2025). "Remarkably, p62 and HDAC6 are associated with aggresomes and the autophagy-derived pathway, which has been reported to act against ZIKV infection." (PMID 38607037, 2024).
abortion (1 paper, 2019). the ending of pregnancy by removing a fetus or embryo before it can survive outside the uterus. "In an effort to identify new potential markers associated with the incidence of abortion, we also described sequence variants in the HDAC6 (histone deacetylase 6) gene given its involvement in controlling PRRSV replication." (PMID 31374992, 2019).
acute leukemia (1 paper, 2018). A clonal (malignant) hematopoietic disorder with an acute onset, affecting the bone marrow and the peripheral blood. "In order to improve efficacy of chemotherapy agents of acute leukemia, this study will investigate the effects of combination MPT0G211, a novel histone deacetylase 6 inhibitor, with doxorubicin or vincristine on human acute leukemia cells." (PMID 30594243, 2018). "Histone deacetylase 6 inhibition is considered as a potential therapeutic strategy for acute leukemia, since it is observed that HDAC6 is overexpressed in acute leukemia and regulates tumor survival." (PMID 30594243, 2018). "We additionally used an MTT assay to evaluate the effects of HDAC6 inhibitors on the viability of acute leukemia cells." (PMID 30594243, 2018). "In this study, we examined the inhibitory effects of MPT0G211 on HDAC6 activity in acute leukemia cells." (PMID 30594243, 2018). "In the present study, we evaluated the effects of a novel, selective HDAC6 inhibitor, MPT0G211, in acute leukemia cells when administered alone or in combination with chemotherapy drugs." (PMID 30594243, 2018).
AIDS (1 paper, 2023). A syndrome resulting from the acquired deficiency of cellular immunity caused by the human immunodeficiency virus (HIV). "HDAC6 inhibitors are being developed to treat immune and inflammatory diseases, including human immunodeficiency virus (HIV)/acquired immunodeficiency syndrome (AIDS)." (PMID 37452321, 2023).
alcoholism (1 paper, 2021). "A previous study showed that HDAC6 is involved in the alcoholism pathway and thus which was associated with chronic inflammation." (PMID 34838026, 2021).
anaemia (1 paper, 2023). "Ricolinostat (ACY‐1215) is a selective inhibitor of the histone deacetylase HDAC6 with proven efficacy in the treatment of malignant diseases, but anaemia is one of the most frequent side effects." (PMID 36578217, 2023).
anaphylaxis (1 paper, 2021). An acute hypersensitivity reaction that occurs from exposure to an allergen. "Global identification of downstream targets of HDAC6 is needed in the future to better understanding the mechanism of HDAC6-promoted anaphylaxis." (PMID 34234781, 2021).
anxiety disorder (1 paper, 2025). A category of psychiatric disorders which are characterized by anxious feelings or fear often accompanied by physical symptoms associated with anxiety. "Given its favorable reproducibility, [18F]Bavarostat shows potential for future PET studies investigating HDAC6 expression, particularly in the assessment of stress and anxiety disorders." (PMID 40542929, 2025).
asthenozoospermia (1 paper, 2021). "Recently, we have reported HDAC6, the tubulin specific deacetylase to be reduced in sperm of men with asthenozoospermia." (PMID 33933143, 2021).
atrial tachycardia (1 paper, 2021). A disorder characterized by an electrocardiographic finding of an organized, regular atrial rhythm with atrial rate between 101 and 240 beats per minute. "The use of HDAC6 inhibitor tubastatin A in vivo can protect dogs with atrial tachycardia pacing from electrical remodeling, while the dominant negative HDAC6 mutant can completely rescue the systolic dysfunction induced by tachycardia pacing." (PMID 35127848, 2021).
Atrophy (1 paper, 2021). Any weakening or degeneration, especially through lack of use. "As for the tubular atrophy/interstitial fibrosis, this study revealed that the HDAC6 positive area of T1 score and T2 score patients were statistically higher than that of T0 score patients." (PMID 33896334, 2021).
benign skin tumours (1 paper, 2025). "The regulation of HDAC6 by cylindromatosis (CYLD), which is a tumour suppressor protein mutated in benign skin tumours, shows that the regulation of HDAC6 activity by protein–protein interactions occurs in cancer." (PMID 39941046, 2025).
bile reflux (1 paper, 2021). "Suppression of the HDAC6/HNF4α loop and restoration of miR-1 may be a promising approach for gastric IM in patients with bile reflux." (PMID 32705446, 2021).
bipolar disorder (1 paper, 2010). A disorder of the brain that causes unusual shifts in mood, energy, activity levels and the ability to carry out day-to-day tasks. "HDAC6 is necessary for the degradation of aggregated hungtingtin, regulates the traffic of parkin, a Parkinson linked protein, and also HDAC6 mRNA levels are significantly decreased in bipolar disorder patients." (PMID 20886111, 2010).
brain inflammation (1 paper, 2019). "Results derived from our study might help reveal the effective targeting strategies of LPS-induced brain inflammation through inhibiting HDAC6." (PMID 31124385, 2019).
breast tumors (1 paper, 2018). "Previous studies have shown that HDACs are overexpressed in ER-α positive breast tumors, and HDAC1, HDAC3 and HDAC6 protein expressions correlate with ER-α expression." (PMID 30352569, 2018).
carotid atherosclerosis (1 paper, 2025). A thickening and loss of elasticity of the walls of carotid arteries that occur with formation of atherosclerotic plaques. "Analysis of monocyte samples from the GSE23746 database revealed that Histone Deacetylase 6 (HDAC6) expression was significantly downregulated in patients with carotid atherosclerosis compared to healthy controls." (PMID 41444216, 2025).
cataract (1 paper, 2020). Partial or complete opacity of the crystalline lens of one or both eyes that decreases visual acuity and eventually results in blindness. "In the current study, we demonstrated that miR‐22‐3p was decreased in both fibrotic plaques from fibrotic cataract patients and under TGF‐β2 stimulation, as well as exerted inhibitory effects on the fibrosis processes through HDAC6." (PMID 32985730, 2020).
Cerebellar medulloblastoma (1 paper, 2017). "Among HDAC inhibitors, selective HDAC6 inhibitors (tubastatin-A (TBSA) and tubacin) concentration-dependently inhibited JEV-induced cytopathic effect and apoptosis, as well as reduced virus yield in human cerebellar medulloblastoma cells." (PMID 28468311, 2017).
Charcot-Marie-Tooth type 2A disease (1 paper, 2023). "Moreover, the degeneration of motor and sensory nerves can be prevented by inhibition of HDAC6 when given either prior to or after the onset of symptoms or by deletion of the gene coding for HDAC6, as shown in a mice model of Charcot-Marie-Tooth type 2A disease." (PMID 37106761, 2023).
chlamydial infection (1 paper, 2017). "Taken together, our findings strongly suggest that Parkin, HDAC6, and HSP25/27 are critically involved in the autophagosomal clearance and MHC I-presentation of chlamydia in infected DCs." (PMID 28634388, 2017).
chronic myelogenous leukemia (1 paper, 2019). "Conversely, the selective HDAC6 inhibitor Rocilinostat, which did not induce SLFN11 in K562 chronic myelogenous leukemia or HT1080 fibrosarcoma cells, was 1.51-fold less potent for CD47− vs. WT cells in the CellTiter Glo assay and was less potent for inhibiting proliferation of CD47− cells." (PMID 31632920, 2019).
clear cell carcinomas (1 paper, 2020). "For example, mutations of the ARID1A gene is associated with increased sensitivity to HDAC6 inhibition in clear cell carcinomas." (PMID 33322608, 2020).
corneal diseases (1 paper, 2025). "In this study, we demonstrate that the level of HDAC6 expression is abnormally elevated in multiple corneal diseases." (PMID 40155750, 2025). "Collectively, these results demonstrate HDAC6 overexpression in corneal diseases, particularly in BK, and indicate a potential role for this protein in regulating corneal epithelial homeostasis." (PMID 40155750, 2025). "In this study, by comparing the transcriptomes of keratoconus, bacterial keratitis, viral keratitis, and healthy corneas, we found a steady upregulation of histone deacetylase 6 (HDAC6) in corneal diseases." (PMID 40155750, 2025). "Interestingly, heatmap visualization revealed that HDAC6 is highly upregulated in corneal diseases compared to healthy corneas." (PMID 40155750, 2025).
dementia (1 paper, 2012). Loss of intellectual abilities interfering with an individual's social and occupational functions. "HDAC6 is concentrated in Lewy bodies in PD and dementia with LBs, and the Drosophila histone deacetylase 6 (dHDAC6) was shown to play a critical role in the protection of dopaminergic neurons and promoted the formation of α-synuclein inclusions in a Drosophila PD model expressing human α-synuclein." (PMID 22623900, 2012).
dermatomyositis (1 paper, 2018). Dermatomyositis (DM) is a type of idiopathic inflammatory myopathy characterized by evocative skin lesions and symmetrical proximal muscle weakness. "In muscle biopsies from dermatomyositis and polymyositis patients, NFAT5 colocalized with HDAC6, while in IBM, this was often absent." (PMID 29515464, 2018).
ductal carcinoma in situ (1 paper, 2021). "Plasma and urine SFN metabolites, PBMC HDAC activity, and tissue biomarkers, such as HDAC3, HDAC6, H3K18ac, H3K9ac, Ki-67, and p21, were measured pre- and post-treatment in benign, ductal carcinoma in situ (DCIS) or invasive ductal carcinoma (IDC) breast tissues." (PMID 34638282, 2021).
Dyskinesia (1 paper, 2023). A movement disorder which consists of effects including diminished voluntary movements and the presence of involuntary movements. "On the other hand, a few studies report that deficiency or inhibition of HDAC6 aggravates dyskinesia in PD animals induced by UPS toxins." (PMID 37373121, 2023).
eczema (1 paper, 2022). "Bufexamac, an aryl alkanoic acid derivative and a nonsteroidal anti-inflammatory agent for the topical treatment of eczema and other inflammatory skin diseases, is a specific inhibitor of the deacetylases of histone types IIB (HDAC6 and HDAC10)." (PMID 35592524, 2022).
endometrial adenocarcinoma (1 paper, 2020). "Both qRT-PCR and Western blotting showed increased expression of HDAC6 in the EC cell lines, with the strongest upregulation in AN3C cells, which are derived from a poorly differentiated human endometrial adenocarcinoma." (PMID 32107418, 2020).
erectile dysfunction (1 paper, 2024). Persistent or recurrent inability to achieve or to maintain an erection during sexual activity. "This was the first study to investigate HDAC6-specific inhibition for treatment of erectile dysfunction." (PMID 39790566, 2024).
experimental autoimmune encephalomyelitis (1 paper, 2019). An autoimmune demyelinating disease of the central nervous system that is produced experimentally in animals by the injection of homogenized brain or spinal cord in Freund's adjuvant. "In this study, experimental autoimmune encephalomyelitis (EAE) mice, an animal model of MS, were treated with the HDAC6 inhibitor drug ACY-738 (20 mg/kg) on day 9 and day 10 post-immunization." (PMID 31316445, 2019).
fibrosarcoma (1 paper, 2013). A malignant mesenchymal fibroblastic neoplasm affecting the soft tissue and bone. "In this study, we showed that exposure of fibrosarcoma cells to hypoxia promoted HDAC6 tubulin deacetylase activity that orchestrated Smad3 activation and nuclear translocation." (PMID 23405166, 2013). "Among the few factors, TGFβ has been shown to induce HDAC6 activity through Smad3 activation in lung epithelial cells and we showed here that stimulation of fibrosarcoma cells with TGFβ enhanced HDAC6 activity." (PMID 23405166, 2013).
fibrosis (1 paper, 2022). the formation of excess fibrous connective tissue in an organ or tissue in a reparative or reactive process. "The inhibition of HDAC6 is reported to exert the anti-fibrotic effect in various fibrosis models." (PMID 35784347, 2022).
gastritis (1 paper, 2021). Inflammation of the stomach. "To investigate the relevance of HDAC6 and HNF4α with gastric IM clinically, we examined the expression of both in normal, gastritis and IM tissues." (PMID 32705446, 2021).
Gaucher disease (1 paper, 2025). Gaucher disease (GD) is a lysosomal storage disorder encompassing three main forms (types 1, 2 and 3), a fetal form and a variant with cardiac involvement (Gaucher disease - ophthalmoplegia - cardiovascular calcification or Gaucher-like disease). "As a lysosomal storage disorder, neuropathic Gaucher disease highlights mechanisms that may be relevant to other inherited metabolic conditions, supporting further investigation of HDAC6 inhibition in diseases such as PKU." (PMID 41274966, 2025).
gout (1 paper, 2023). A condition characterized by painful swelling of the joints, which is caused by deposition of urate crystals. "Further studies are needed to verify the therapeutic effect of the HDAC6 inhibitor on the treatment of bone erosion in gouty arthritis." (PMID 36986544, 2023). "The role of HDAC6 in the regulation of osteoclasts in bone damage in the pathogenesis of gout is not fully determined." (PMID 36986544, 2023). "Studies have shown that HDAC6 is involved in the activation of the NACHT, LRR, and PYD-domains-containing the protein 3 (NLRP3) inflammasome, playing an important role in the pathological mechanism of gout." (PMID 36986544, 2023). "The purpose of this study was to identify whether HDAC6 inhibition could attenuate osteoclast differentiation and formation through the RANK-RANKL-NFATc1 pathway in gout." (PMID 36986544, 2023). "Whether HDAC6 is involved in or responsible for MSU-induced bone damage in gout had not been examined." (PMID 36986544, 2023). "Furthermore, the HDAC6 inhibitor CKD-WID has not been well studied regarding its therapeutic role in MSU crystal-mediated bone damage in the pathogenesis of gout." (PMID 36986544, 2023).
hemorrhage (1 paper, 2023). Loss of blood from the vascular compartment to the exterior or into nonvascular body space as a result of rupture or severance of the blood vessels. "In this study, we used hemin-induced SH-SY5Y cells to simulate a hemorrhage state in vitro and adopted a collagenase-induced ICH rat model in vivo to assess the effect of the HDAC6 inhibition." (PMID 37138816, 2023).
herpes simplex encephalitis (1 paper, 2025). Herpes simplex virus encephalitis (HSE) is caused by the infection of the central nervous system by Herpes simplex virus (HSV) that could have a devastating clinical course and a potentially fatal outcome particularly with delay or lack of treatment. "Consistent with the in vitro results, HDAC6 knockout (KO) mice were resistant to HSV-1 infection and herpes simplex encephalitis (HSE) pathogenesis." (PMID 39747662, 2025).
IgA nephropathy (1 paper, 2021). "If possible, we need to explore the effect of HDAC6 on the development of IgA nephropathy in animal models in our future studies." (PMID 33896334, 2021). "Third, we should perform the follow-up study to obtain more convincing data to address the correlation between HDAC6 expression and clinical outcomes in IgA nephropathy patients in the near future." (PMID 33896334, 2021). "As far as we know, this is firstly demonstrated that the HDAC6 highly expressed in patients with IgA nephropathy is tightly correlated with renal dysfunction." (PMID 33896334, 2021). "In conclusion, the results of this study identified that the expression of HDAC6 was increased in the IgA nephropathy." (PMID 33896334, 2021). "In our study, we found that HDAC6 highly expressed in patients with IgA nephropathy is tightly correlated with renal dysfunction, these might suggest that the expression of HDAC6 could be a potential prognosis factor for IgAN." (PMID 33896334, 2021). "However, correlation between HDAC6 and clinical parameters in IgA nephropathy (IgAN) patients is still unknown." (PMID 33896334, 2021). "However, it remains unclear whether HDAC6 also participated in the progression of IgA nephropathy." (PMID 33896334, 2021).
intestinal obstruction (1 paper, 2017). Blockage of the normal flow of the intestinal contents within the bowel. "Consistent with their CF counterparts, the majority of deaths resulted from intestinal obstruction, indicating that HDAC6 has no implications on the gastrointestinal complications that are often observed in CF animals and patients." (PMID 28623308, 2017).
invasive ductal breast carcinoma (1 paper, 2021). The most common type of invasive breast carcinoma, accounting for approximately 70% of breast carcinomas. "In comparison, high HDAC-6 expression has been associated with younger patients’ age in invasive ductal breast carcinoma cases." (PMID 33799478, 2021).
keratitis (1 paper, 2025). A corneal disease that is characterized by inflammation of the cornea. "These accumulating results, along with our finding that HDAC6 overexpression thickens the corneal epithelium and disturbs corneal homeostasis, suggest that targeting HDAC6 may hold promise for the management of ocular diseases, including keratoconus and keratitis." (PMID 40155750, 2025).
kidney cancer (1 paper, 2021). Primary or metastatic malignant neoplasm involving the kidney. "A similar study was carried out in kidney cancer, showing an increase of cell migration after HDAC6 overexpression." (PMID 34073238, 2021).
liver disease (1 paper, 2025). "However, other research has demonstrated HDAC6's opposing roles in liver regeneration and hepatocarcinogenesis, which underscores its complexity in liver disease and warrants further investigation." (PMID 40084612, 2025).
lymphoproliferative disorders (1 paper, 2018). "In this review, we describe the HDACs, their inhibitors, and the recent advances of HDAC6 inhibitors, their mechanisms of action and role in lymphoproliferative disorders." (PMID 30096875, 2018).
malignant glioma (1 paper, 2017). A grade III or grade IV glioma arising from the central nervous system. "Furthermore, we investigated whether TDP-43 and HDAC6 were dysregulated in a correlated manner in malignant glioma." (PMID 28915616, 2017).
metastatic disease (1 paper, 2023). "Therefore, considering the role of HDAC6 in hypoxia-induced metastatic invasion to regional lymphatics, the therapeutic targeting of HDAC6 may have important therapeutic implications for the treatment of metastatic disease." (PMID 38258065, 2023).